SART1 (spliceosome associated factor 1, recruiter of U4/U6.U5 tri-snRNP)
Description:
Plays a role in mRNA splicing as a component of the U4/U6-U5 tri-snRNP, one of the building blocks of the spliceosome. May also bind to DNA.
Synonyms: Ara1; Snu66; SNRNP110; HAF; HOMS1; SART1259
Tractability: Small molecule: a structure with a bound ligand is known. PROTAC: UniProt records ubiquitination sites on it; ubiquitination databases record sites on it; its protein half-life has been measured.
Gene: Protein-coding gene on chromosome 11 (65,961,689 to 65,980,137, forward strand). Ensembl gene ENSG00000175467.
Subcellular location: Nucleus
Subcellular location (Human Protein Atlas): Nuclear speckles; Golgi apparatus
Pathways (Reactome):
Metabolism of RNA: mRNA Splicing - Major Pathway
Gene Ontology:
Molecular function: protein binding; RNA binding
Biological process: mRNA splicing, via spliceosome; positive regulation of cytotoxic T cell differentiation; maturation of 5S rRNA; mRNA cis splicing, via spliceosome; spliceosomal snRNP assembly; spliceosomal tri-snRNP complex assembly; spliceosome conformational change to release U4 (or U4atac) and U1 (or U11)
Cellular component: Cajal body; catalytic step 2 spliceosome; Golgi apparatus; nuclear speck; nucleoplasm; nucleus; precatalytic spliceosome; spliceosomal complex; U12-type precatalytic spliceosome; U2-type precatalytic spliceosome; U4/U6 x U5 tri-snRNP complex; cytoplasm; cytosol; U4atac/U6atac x U5 tri-snRNP complex
Genetic constraint (gnomAD): Loss-of-function variants: 27 observed, 95.46 expected, observed/expected ratio (o/e) 0.28, 90% interval 0.21 to 0.39. The upper end of that interval is the gene's LOEUF score, 0.39, which puts it in group 1 of 6, group 1 being the genes least tolerant of losing a copy. Missense variants: 859 observed, 1,011.7 expected, observed/expected ratio (o/e) 0.85, 90% interval 0.8 to 0.9. Synonymous variants: 454 observed, 426.72 expected, observed/expected ratio (o/e) 1.06, 90% interval 0.98 to 1.15.
Homologues: Orthologues: chimpanzee SART1 (99% identical), macaque SART1 (99% identical), dog SART1 (97% identical), pig SART1 (96% identical), mouse Sart1 (95% identical), rat Sart1 (95% identical), guinea pig SART1 (81% identical), Drosophila melanogaster CG6686 (40% identical), Caenorhabditis elegans snu-66 (32% identical).
Diseases named in the same sentence as SART1 in open-access papers:
SART1 is named in the same sentence as 33 diseases in open-access papers, as found by Europe PMC text mining. Sharing a sentence is not in itself a finding about the gene and the disease. The quoted sentences say what the papers report.
breast carcinoma (6 papers, 2011 to 2024). "Particularly, the breast cancer associated allele of rs660118 SNP in the gene SART1 showed a near doubled frequency in glioblastoma patients, as verified in an independent control cohort by Sanger sequencing." (PMID 21695249, 2011). "Hence, the elevated expression of TMEM24 and SART1 may be linked to increased cell proliferation in breast cancer." (PMID 39004717, 2024). "During STRING analysis, we found ESF1, MIPEP, TMEM24, and SART1 were the hub genes in ER + breast cancer’s pathogenesis." (PMID 39004717, 2024). "SART1 was also shown to be essential for cell division in breast cancer cells, and siRNA-mediated down-regulation of SART1 resulted in increased apoptosis." (PMID 36265897, 2023). "As a bicistronic gene, SART1 participates in the initiation and development of HNSC and colorectal cancer and is an essential gene for breast cancer cell division." (PMID 36081672, 2022).
colorectal cancer (3 papers, 2011 to 2025). A primary or metastatic malignant neoplasm that affects the colon or rectum. "The SNP rs660118 maps within the SART1 (squamous cell carcinoma antigen recognized by T cells) gene that is also known as tumor-rejection antigen in brain tumors and in a range of other tumors including hepatocellular carcinoma, colorectal cancer, renal cell carcinoma, and osteosarcoma." (PMID 21695249, 2011).
glioma (3 papers, 2014 to 2017). A benign or malignant brain and spinal cord tumor that arises from glial cells (astrocytes, oligodendrocytes, ependymal cells). "Many of these up-regulated TAPPs are common in gliomas and other brain cancers, such as Aim2, EZH2, GP100, Mage-1, MageA4, MageA10, Sart-1, -3, Trp-1, and Sox2." (PMID 26175925, 2015).
osteosarcoma (3 papers, 2005 to 2021). A usually aggressive malignant bone-forming mesenchymal neoplasm, predominantly affecting adolescents and young adults. "Indeed, several tumor antigens such as melanoma-associated antigen (MAGE), squamous cell carcinoma antigen recognized by T cells (SART) 1, SART3 and papillomavirus binding factor are expressed in osteosarcoma and provided the rationale to develop cellular therapies for this pathology." (PMID 16188028, 2005).
esophageal squamous cell carcinoma (2 papers, 2023 to 2025). Esophageal squamous cell carcinoma (ESCC) is a type of esophageal carcinoma (EC) that can affect any part of the esophagus, but is usually located in the upper or middle third. "Additionally, in a phase I/II study in Japan, SART1-pulsed Dex enhanced cytotoxic T-cell responses in patients with advanced squamous cell carcinoma of the esophagus." (PMID 37371709, 2023).
melanoma (2 papers, 2013 to 2015). A malignant, usually aggressive tumor composed of atypical, neoplastic melanocytes.
renal cell carcinoma (2 papers, 2011 to 2024). "SART1 is a spliceosome protein that mediates the degradation of the HIF1-α protein and facilitates the proliferation of renal cell carcinoma (RCC) cells." (PMID 39004717, 2024).
autosomal dominant neovascular inflammatory vitreoretinopathy (1 paper, 2008). "SART1/HAF is on 11q13, where a locus for the autosomal dominant neovascular inflammatory vitreoretinopathy (VRNI) was mapped (OMIM 193235)." (PMID 18334927, 2008).
brain ischemia (1 paper, 2008). Diminished or absent blood supply to the brain caused by obstruction (thrombosis or embolism) of an artery resulting in neurologic damage. "The original data set of our cDNA microarray study in brain ischemia showed a trend for down-regulation of the mouse Sart1 mRNA (−1.5) that was measured with the probe sequence AA607769 (Nucleotide, NCBI)." (PMID 18334927, 2008).
chronic hepatitis B (1 paper, 2016). "In this study, we investigated the role of SART1 in antiviral activity of IFN-α against hepatitis B virus (HBV) using blood and liver biopsy samples from chronic hepatitis B patients treated with pegylated IFN-α and HepG2 cells transfected with cloned HBV DNA." (PMID 28077916, 2016).
disc degeneration (1 paper, 2025). "In severe disc degeneration, RCOR2, STAT3, NOTCH1, SP1, and SART1 expression were elevated, while PRIM1 and LYAR expression levels were significantly reduced." (PMID 40799650, 2025).
head and neck squamous cell carcinoma (1 paper, 2011). A squamous cell carcinoma that arises from any of the following anatomic sites: lip and oral cavity, nasal cavity, paranasal sinuses, pharynx, larynx, and salivary glands. "Amplification and overexpression of SART1 occurs in head and neck squamous cell carcinoma (HNSCC)." (PMID 21695249, 2011).
Hepatitis C infection (1 paper, 2015). "We hypothesize that SIRT1 may contribute to the defense mechanism by modifying the acetylation and activity of SART1 during Hepatitis C infection." (PMID 26468954, 2015).
intervertebral disc degeneration (1 paper, 2025).
lung adenocarcinoma (1 paper, 2019). A carcinoma that arises from the lung and is characterized by the presence of malignant glandular epithelial cells. "Focusing on the direct association supported by the literature, the searching results elucidated that for the AC & stage category, only ALCAM, TYR and SART1 are related to lung adenocarcinoma but with very low confidence scores (1.60, 0.25 and 0.25 respectively)." (PMID 30971213, 2019).
pulmonary fibrosis (1 paper, 2021). Chronic progressive interstitial lung disorder characterized by the replacement of the lung tissue by connective tissue, leading to progressive dyspnea, respiratory failure, or right heart failure. "Collectively, both human and mouse experiments have shown that the remarkable overexpression of Sart1 emerged in lung macrophages during the pathogenic process of pulmonary fibrosis." (PMID 33391530, 2021). "Since IPF patients and mice were characterized by the overexpression of Sart1 in macrophages, we next sought to assess the therapeutic effect of Sart1 siRNA on pulmonary fibrosis model by employing Sart1 siRNA-loaded liposomes." (PMID 33391530, 2021). "We further noted that macrophages originating from the lungs of patients with IPF and pulmonary fibrosis model mice exhibited significantly upregulated Sart1 expression." (PMID 33391530, 2021). "In summary, our data suggest that suppressing Sart1 by siRNA-loaded liposomes could be a promising strategy for the treatment of pulmonary fibrosis in clinical settings." (PMID 33391530, 2021). "Additionally, the Sart1 siRNA-loaded liposomes-treated group achieved a lower Ashcroft score, indicating relief from pulmonary fibrosis." (PMID 33391530, 2021). "This study suggests that Sart1 siRNA-loaded liposomes may be a promising therapeutic strategy for pulmonary fibrosis in clinical settings." (PMID 33391530, 2021). "Similarly, Western blot and RT-PCR analyses revealed extremely increased Sart1 expression in the lungs of pulmonary fibrosis-bearing mice compared to control mice." (PMID 33391530, 2021). "Herein, we demonstrated that SART1 was mainly overexpressed in macrophages in the lungs of IPF patients and pulmonary fibrosis model mice." (PMID 33391530, 2021). "Interestingly, notable overexpression of SART1 was observed in macrophages originating from IPF patients and mice with pulmonary fibrosis." (PMID 33391530, 2021). "In addition, Sart1 siRNA-loaded liposomes administered via intratracheal injection could effectively target pulmonary fibrotic areas and greatly protected mice from BLM-induced pulmonary fibrosis." (PMID 33391530, 2021).
cancer (11 papers, 2002 to 2025). A tumor composed of atypical neoplastic, often pleomorphic cells that invade other tissues. "Therefore, SART1 has been considered a potential diagnostic marker and therapeutic target in various cancers." (PMID 40320072, 2025). "The SART1 protein is expressed in most proliferating cells but overexpressed in some cancer cells, including epithelial cancers." (PMID 40320072, 2025). "For instance, a pancancer analysis has revealed that TRMT112 expression is positively correlated with SART1 expression in various cancers, including HNSCC." (PMID 41235342, 2025). "In human cells, increased expression of SART1 in different cancer cell lines leads to cell division defects and apoptosis and correlates with altered expression of important cell cycle regulators." (PMID 36265897, 2023). "In addition to splicing, Sart1 has been implicated in a number of different processes such as cell cycle arrest and apoptosis and has been suggested as a target for gene therapy due to its role as an antigen recognized by cytotoxic T-lymphocytes (CTLs) in certain types of cancer." (PMID 33105605, 2020). "SART1 was originally identified as a tumor antigen in a range of cancers recognized by T cells." (PMID 36265897, 2023). "More recently, Sart1 has been shown to contribute to drug resistance in cancer cells." (PMID 33105605, 2020). "Understanding Sart1 regulation of gene expression will reveal how spliceosome components not only play a role in splicing, but also other cellular processes, such as apoptosis, and pathological conditions, such as degeneration and cancer." (PMID 33105605, 2020). "Sart1 has been demonstrated to be involved in apoptosis where it appears to play a dual role by inducing cell cycle arrest, but also aiding in drug resistance in cancer cells." (PMID 33105605, 2020). "The altered expression level of hub SFs has been reported in multiple types of cancer, such as YBX1, SART1, SNRPE, and SF3B4." (PMID 33101358, 2020). "We have used self-antigen-derived peptides, such as SART1, SART3, and lck, in phase I clinical studies of individualised peptide vaccination for far advanced cancer patients." (PMID 15083186, 2004). "In regard with SART-1, -2, -3, and ART4 antigens, we previously reported their protein expression in many samples of the majority of epithelial cancer cells and tissues by Western blot and Northern analyses." (PMID 12232766, 2002). "Summarizing the data of more than 400 cases including cancer sera, sera of patients with non-cancer diseases and healthy controls, we found an overall 10% increase of autoantibody response to SART1 in cancer sera as compared to normal controls and non-cancer diseases." (PMID 21695249, 2011).
tumor (4 papers, 2003 to 2020). "Based on the reported evidence that SART1 is a tumor antigen we reviewed our own data on antigens that are reactive with tumor sera." (PMID 21695249, 2011).
SART1 also shares sentences with these, for which no sentence is quoted: pancreatic cancer (2 papers); bladder cancer (1); brain tumors (1); gastric cancer (1); glioblastoma (1); Hepatitis B Infection (1); hepatocellular carcinoma (1); Hypercholesterolemia (1); malaria (1); neurodegenerative disease (1); non-alcoholic steatohepatitis (1); oral squamous cell carcinoma (1); retinal degeneration (1); squamous cell carcinoma (1); viral infection (1).